FOS (Fos proto-oncogene, AP-1 transcription factor subunit)
Diseases named in the same sentence as FOS in open-access papers (continued):
Sharing a sentence is not in itself a finding about the gene and the disease.
tumor (continued). "Iron overload has been linked to a poor prognosis in AML, as it contributes to oxidative stress, which promotes neoplastic cell proliferation and increases tumor burden by upregulating oncogenes such as FOS." (PMID 40583922, 2025). "The transcriptomic data showing upregulation of cytolytic genes (GZMs, PRF1) and survival regulators (FOS/JUN family) in the 15.CAR-T cells offers a mechanistic explanation for their superior anti-tumor activity." (PMID 41154636, 2025). "The positive expression of FOS protein was then detected in tumors obtained from tumor-bearing mice treated with different doses of LNT." (PMID 40089488, 2025). "Analysis of cell proliferation in vitro and EC growth in vivo strongly indicated that SF3A3 and c‐FOS have tumor‐suppressive effects." (PMID 40598817, 2025). "The FOS gene is involved in multiple tumorigenic processes such as cell motility, proliferation, tumor growth, metastasis, and angiogenesis." (PMID 40722651, 2025). "Our study fills this important gap by identifying SF3A3 as a novel oncogenic regulator in EC, functioning through direct regulation of c‐FOS alternative splicing, which promotes tumor proliferation and chemoresistance." (PMID 40598817, 2025). "Previous studies have demonstrated that the overexpression of FOS can promote tumor growth and metastasis." (PMID 40649749, 2025). "Targeting c-FOS therapy can improve the tumor microenvironment, thereby inhibiting tumor growth and lung metastasis, but further research and clinical trials are still needed." (PMID 40148973, 2025). "The importance of the ROR1-GRB2-c-FOS pathway is underscored by findings that artificial expression of c-Fos reverses the tumor-suppressing effects seen when ROR1 is silenced." (PMID 40869147, 2025). "Targeting SF3A3 with phenylethyl isothiocyanate (PEITC) effectively suppresses tumor progression, induces apoptosis, and reduces c‐FOS expression in vitro, in vivo, and patient‐derived tumor‐like cell clusters (PTCs)." (PMID 40598817, 2025). "JUN/FOS regulate proliferation, differentiation, apoptosis, and inflammation, with aberrant activation promoting tumor growth and invasion, while ITGB1 critically mediates cell adhesion, migration, and signaling." (PMID 40725477, 2025). "FOS encoded leucine zipper proteins that dimerize with proteins from the JUN family to form the TF complex AP-1, which played a key role in tumor cell growth, differentiation, survival, and DNA damage response." (PMID 40936936, 2025). "FOS is a proto-oncogene and it can be activated to exert tumor-promoting function in various human cancers through regulating cell cycle progress and apoptosis." (PMID 40089488, 2025). "GSVA scores for the mouse‐mapped PI3K‐Akt and MAPK pathways positively correlated with FOS expression in human tumor tissues (p < 0.001)." (PMID 41024433, 2025). "Driving lipid metabolic reprogramming and immunosuppression through MIF-(CD74+CD44)-mediated macrophage polarization, our work finds FOS as a master regulator of the malignant C0 MAFF+ tumor cell subtype in LUAD." (PMID 40936936, 2025). "The results indicated that c-FOS targeted therapy effectively reduced the Ki67 positive rate in tumors, inhibited angiogenesis, and enhanced tumor cell apoptosis." (PMID 40148973, 2025). "Its overexpression promotes tumor growth, cisplatin resistance, and apoptosis suppression through regulation the alternative splicing of c‐FOS." (PMID 40598817, 2025). "In several types of cancer, high c-FOS is oncogenic and promotes tumour growth, cancer cell stemness and metastasis, and is a marker of poor overall survival." (PMID 40438247, 2025). "FOS expression has been observed in cases of neurological defects and immunodeficiency as well as in tumor progression." (PMID 39466748, 2024).
tumor (continued). "While JUND and JUNB demonstrate tumor-suppressive activity, JUN and FOS frequently display oncogenic characteristics when acting as either tumor suppressors or oncogenes in cancer." (PMID 38674385, 2024). "For example, YAP-regulated enhancers often contain both TEAD and AP-1 motifs, where YAP synergizes with JUN/FOS to promote tumor cell proliferation and transformation." (PMID 38182898, 2024). "In particular, the FOS gene demonstrated a noticeable increase in staining in tumor cells, indicating enhanced expression in the cancerous tissues." (PMID 39682150, 2024). "Further multivariate analysis unveiled significant insights: LRP1, PAEP, PI3, OBP2A, and IL27RA genes exhibited higher levels in the tumour group, whereas FOS, PDGFRA, and FGF7 showed higher expression in normal ovarian tissue (all p < 0.001)." (PMID 39063239, 2024). "FOS expression is regulated by mir‐335‐5p in malignant thyroid carcinoma, indicating its role in tumour development." (PMID 38818568, 2024). "Gene expression analysis of tumor samples showed decreased FOS expression during treatment and re-expression during treatment withdrawal compared to untreated controls, in line with MAPK pathway regulation patterns observed in vitro." (PMID 38630384, 2024). "Several hypoxia-related DEGs showed a highly correlated relationship to their expression levels in tumor samples, such as FOS and DUSP-1." (PMID 36675190, 2023). "Previous studies have reported that FOS participates in tumour metastasis by upregulating the expression of EMT‐related markers as a transcription factor." (PMID 38082402, 2023). "FOS, SERPINE1, AKR1C3, and FGF2 are the genes that potentially play important roles in HCC and are associated with tumor growth." (PMID 37057280, 2023). "FTO restrains tumour metastasis and aggressiveness in EBVaGC by down‐regulating FOS in an m6A‐dependent manner." (PMID 38082402, 2023). "The specific FOS/JUN protein composition of AP-1 was found to regulate the ability of AP-1 to promote or inhibit tumor growth." (PMID 36980293, 2023). "Future work will be required to investigate the relationship between MTF-1 and FOS/JUN in tumor progression." (PMID 36980293, 2023). "We further demonstrate that rearrangements in FOSL1 and, less commonly FOS represent a recurrent and specific feature in the majority of these tumours." (PMID 36426824, 2023). "The expression level of FOS in GC was confirmed by immunohistochemical staining, and the results showed that FOS expression in tumor tissue was significantly higher than that in normal tissues." (PMID 36609277, 2023). "In groups A5, A6, A7, and A8, genes such as CXCL13, HSPA1A, CREM, CCL4, and FOS were highly expressed in CD8+ or CD4+ T cells in tumor tissues." (PMID 37762493, 2023). "For example, many YAP-regulated enhancers contain both TEAD and AP-1 motifs where YAP synergizes with JUN/FOS to promote tumor cell proliferation and transformation." (PMID 36864753, 2023). "The results were in accordance with the difference analysis of hub genes (ANGPT2, VCAN, MS4A4A, and FOS) between tumor tissues and normal tissue." (PMID 36569220, 2022). "FOS was more highly expressed in macrophages (P value-adj = 3.98E − 23) and B cells (P value-adj = 2.56E − 162) of adjacent tissue samples than tumor samples." (PMID 36569220, 2022). "ZFP36 is downregulated in the tumor compared with normal samples, and co‐expressed with JUN, JUNB, FOS, and FOSB, downregulation of which was associated with poor outcomes and BC progression." (PMID 35037412, 2022). "ReactomeFIViz enrichment analysis in Cytoscape showed an association of seven (EDNRB, CDKN2A, VEGFD, FOS, GNG11, TGFBR2, and BIRC5) of the forty-four nodes of the LC-BC CCPs with signaling pathways related with the acquisition of tumor characteristics." (PMID 36101460, 2022).
tumor (continued). "The LC-BC CCPs formed have no more than 12 nodes and identified only seven genes (EDNRB, CDKN2A, VEGFD, FOS, GNG11, TGFBR2, and BIRC5) compromised in signaling pathways associated with the acquisition of tumor characteristics." (PMID 36101460, 2022). "The identified families of genes, encoding keratins, extracellular matrix proteins, protein trafficking and TGF-β, FOS, and Ser/Thr protein kinase proteins contribute to tumor progression, cell invasion, and metastasis in KLK6-overexpressed CRCs." (PMID 34065672, 2021). "CCT5, LCOR, and ZNF367 were evidently overexpressed in tumor tissues compared with adjacent tissues (all P < 0.001), while FOS was significantly downregulated in tumor tissues compared with non-tumor tissues of HCC patients (P < 0.001)." (PMID 34522182, 2021). "We demonstrated a tumor suppressor function of FOS in PCa by analyzing expression data from publicly available datasets." (PMID 34548912, 2021). "Accordingly, we found that tumor tissues obtained from digoxin-treated NMTC patients exhibited higher nuclear FOS expression than their matched control NMTC patients." (PMID 33534128, 2021). "In mouse tumors, the number of tumor cells with FOS-positive nuclei was evidently increased after digoxin treatment." (PMID 33534128, 2021). "Of which, SMAD2, PPP3CA, MAPK1, and FOS genes are known to be involved in the regulation of tumor cell proliferation and invasion." (PMID 33959508, 2021). "FOS can also drive tumor transformation and malignant progression by regulating a variety of tumor-related target genes." (PMID 33149754, 2020). "NK_c3 and NK_c5 were mainly derived from non-tumor liver tissues (23.57% and 5.97%, respectively) and characterized by high expression of transcription factors such as FOS, FOSB, FOXP1, and ATF4, and two genes involved in the NF-κB pathway, NFKBIA and NFKBIZ." (PMID 33298893, 2020). "Although, AP-1 proteins are primarily considered to be oncogenic, recent studies revealed that JUNB and c-FOS proteins display a tumor-suppressor activity as well." (PMID 32296574, 2020). "This is intriguing as in human tumours FOS and FOSB rearrangements have so far only been identified in vascular and bone forming tumours lacking malignant potential." (PMID 31741049, 2020). "Normally, FOS protein plays a major role in several cellular functions, and its overexpression has been observed in many neoplasias." (PMID 32714860, 2020). "The mRNA levels of Ccr7, Mmp9, c-Fos (Fos proto-oncogene, AP-1 transcription factor subunit), c-Jun (Jun), Ccl19 (C-C motif Chemokine Ligand 19) and Ccl21 were significantly reduced in tumor of CRE treated mice." (PMID 30781353, 2019). "Previous reports revealed that FOS exhibited tumor suppressor activity and played significant roles in apoptosis." (PMID 31261921, 2019). "The up-regulation of FOS inhibited cell cycle progression, induced cell death, and suppressed tumor formation." (PMID 31261921, 2019). "Both strands of imR-140 can target FOS thus inhibit tumour cell invasion and modulate their transformation." (PMID 30559931, 2018). "To further investigate the underlying mechanism of RCC angiogenesis, we referred to the KEGG pathway and found that c-FOS was involved in regulation of VEGF contributing to tumor angiogenesis." (PMID 30158581, 2018). "In these 55 samples, we found FOSB and FOS breakapart signals in 1 and 48 tumours, respectively (89% in total)." (PMID 29858576, 2018). "The most highly upregulated genes (e.g. CYR61, DUSP1, FOSB and FOS), which increased in almost all tumours, were early-response genes." (PMID 29214214, 2017). "Two components of AP-1, c-JUN, and c-FOS, are well known as oncoproteins, but in some cases they can suppress tumor formation." (PMID 27270647, 2016).
tumor (continued). "The percent of viable tumor is 85.6% in Ad-FOS-TK group, 81.8% in Ad-CMV-TK group, and 87.1% in PBS group." (PMID 26571389, 2015). "The expression of FOS protein was found to be increased in other tumor types including cervical cancer, squamous cell cancer, and endometrial cancer." (PMID 26571389, 2015). "A number of studies have investigated the oncogenic functions of FOS and found its target genes to be critical for tumorigenesis, responsible for invasive growth of tumor cells and inhibition of tumor suppressor activity." (PMID 26571389, 2015). "We also tested the biologic activity of recombinant adenovirus containing the suicide gene herpes simplex virus thymidine kinase (HSV-tk) driven by the FOS promoter, including selective killing efficacy in vitro and tumor inhibition rate in vivo." (PMID 26571389, 2015). "The tumor volume in the mice treated with Ad-FOS-HSVtk-IRES-GFP was significantly smaller than that of the vehicle control group from day 15 onwards." (PMID 26571389, 2015). "Among these, we validated EZH2, MCL-1 and FOS as direct targets of miR-101 and silencing of these genes mimics the tumor suppressive effects observed on promoting microRNA-101 function." (PMID 25153722, 2014). "Analysis of the microarray data showed FOS upregulated in the tumor class of the CMS with a fold change of 1.7, and a fold change 2.5 times higher in WNiCo than Ta." (PMID 24619124, 2014). "nc886's tumor suppressive role is corroborated by the induction of well-known oncogenes such as FOS, NF-κB, and MYC upon its knockdown." (PMID 25003254, 2014). "Studies on the oncogenic functions of FOS show it to be involved in the regulation of tumorogenesis, leading to down-regulation of tumor suppressor genes and eventually to invasive growth of cancer cells." (PMID 22236809, 2012). "MYC, BMP2, and FOS show an associative trend when overexpressed, and TNFRSF10A shows a trend in underexpression in the tumor cohort." (PMID 20465837, 2010). "Furthermore, radiomic features have revealed to be superior to FOS as predictors for VS tumor growth, while preserving a degree of model explainability." (PMID 41457855, 2026). "Thus, it would be very interesting to elucidate the mechanism that confers the oncogenic or tumor-suppressor role to FOS across different cancer types, though it is out of the scope of our current study." (PMID 40093906, 2025). "Finally, tumor migration experiments revealed that inhibiting c-FOS in neutrophils can reduce the promoting effect of neutrophils on the migration of MDA-MB-231 and HCC1937 cells." (PMID 40148973, 2025). "Targeting c-FOS therapy can effectively inhibit tumor growth and lung metastasis." (PMID 40148973, 2025). "Finally, to clarify the mechanism of c-FOS targeted therapy in tumor growth and lung metastasis, we assessed tumor proliferation ability, vascular density, and cell apoptosis." (PMID 40148973, 2025). "Additionally, FOS acts as a critical tumor-suppressor and CoREST-independent target of ZNF217 in B-ALL." (PMID 40093906, 2025). "Inhibition of c-FOS can suppress tumor growth and lung metastasis in TNBC." (PMID 40148973, 2025). "The tumor cell growth was significantly reduced in vitro and in vivo following FOS knockout." (PMID 40151836, 2025). "Importantly, the combination of PEITC and the c‐FOS inhibitor T‐5224 demonstrated synergistic effects in patient‐derived tumor‐like cell clusters (PTCs)." (PMID 40598817, 2025). "Leveraging advanced bioinformatics techniques, the identification of 12 crucial genes (ETNK1, BICRA, IL-1R1, KDM3A, ARID2, GSK3β, EZH2, NOTCH1, SMARCA4, FOS, CREB1, CASP3) associated with the tumor-suppressing miR-101-3p network stands out as a notable achievement." (PMID 40074445, 2025).
tumor (continued). "Mechanistically, SF3A3 regulates apoptosis and contributes to drug resistance, at least partially by modulating the AS of fos proto‐oncogene, AP‐1 transcription factor subunit (c‐FOS), a proto‐oncogene involved in cellular proliferation, drug resistance, and tumor growth." (PMID 40598817, 2025). "The upregulation of compensatory survival pathways, specifically the HALLMARK_TNFA_SIGNALING_VIA_NFKB gene set involving high levels of FOS in LA fusion tumor cells, may explain this resistance." (PMID 40151836, 2025). "Likewise, FOS expression was decreased more in tumor tissues obtained from model mice treated with higher dose of LNT." (PMID 40089488, 2025). "The upregulation of activating transcription factors FOS and JUN was also detected in TRNA samples when compared to BPH samples, the expression of which has been previously linked to epithelial cell stress response in tumor progression." (PMID 39550375, 2024). "The involvement of FOS in innate immunity and neoplasia has also been documented." (PMID 39261458, 2024). "Key signaling molecules, including transforming growth factor beta (TGFβ) related to SRC, interleukin 1 (IL-1) associated with FOS, CXC chemokine (CXCL2), and vascular endothelial growth factor (VEGF), were highlighted due to their critical roles in tumor initiation, progression, and deterioration." (PMID 39770551, 2024). "After the identification of malignant cells from epithelial cells, we observed seven subtypes of malignant cells that reflect heterogeneous status in tumor, including tumor_CAV1, tumor_ATF3_JUN | FOS, tumor_ZEB2, tumor_VIM, tumor_WSB1, tumor_LXN, and tumor_PGM1." (PMID 38729966, 2024). "FOS affects tumor progression by regulating the Ras-ERK or PI-3K-AKT pathway." (PMID 38155938, 2023). "FOS is ubiquitous in a variety of cancers and is a powerful driving force for tumor development." (PMID 36609277, 2023). "In particular, FOS downregulates MAPK/ERK pathway, a cascade of subsequent protein activation that communicates signals from membrane receptors to the cell nucleus, causing tumor growth." (PMID 37511359, 2023). "Moreover, an IHC staining assay was conducted to explore the correlation between FTO and FOS in vivo and revealed that silencing FTO elevated FOS expression in tumour tissues." (PMID 38082402, 2023). "The panels were designed to identify cytotoxic T cells (CD8+ GZMB+ CD3+), myeloid-derived suppressor cells (MDSCs) (CD11b+ CD33+ HLA-DR-negative) and B cells (CD20+ CD79a+), as well as a panel with CD3 and FOS to confirm the high expression of FOS in the tumour cells." (PMID 36982943, 2023). "Though AP-1 family proteins have long been recognized as oncoproteins, it is poorly understood whether c-FOS controls tumor cell fate and how c-FOS is regulated in the activation of EMT during mammary tumorigenesis." (PMID 37353480, 2023). "In this study, we found that the hub genes including VCAN MS4A4A, and FOS could regulate the differentiation of monocytes in the tumor environment." (PMID 36569220, 2022). "FOS+ Macrophages cells are more likely to promote inflammation and tumor growth." (PMID 36569220, 2022). "It will be exciting to see whether other tumor entities also rely on c‐FOS for survival upon treatment with clinically applicable HDACi." (PMID 35604882, 2022). "Tumour-specific hypomethylation events were enriched in TF binding motifs of the JUN/FOS proteins, building blocks of the activator protein-1 (AP-1) transcription factor known for their role in lung tumorigenesis as well as their involvement within other signal transduction pathways." (PMID 35931677, 2022). "Whether, the third residual cell population emerging in the dacinostat high‐dose setting, characterized by low c‐FOS expression, contributes to the tumor outgrowth, and can be targeted, remains to be clarified." (PMID 35604882, 2022).